EZH2 (enhancer of zeste 2 polycomb repressive complex 2 subunit)
Diseases named in the same sentence as EZH2 in open-access papers (continued):
Sharing a sentence is not in itself a finding about the gene and the disease.
Weaver syndrome (continued). "Genetic testing can assist in establishing a diagnosis: The genetic change associated with Weaver syndrome is in EZH2, a histone methyltransferase, which is an important component of the highly conserved repression complex PRC2 (polycomb repressive complex 2)." (PMID 33194904, 2020). "EZH2 was the first PRC2 subunit to be implicated in Weaver syndrome, with a predominance of missense mutations reported throughout the EZH2 gene." (PMID 31575610, 2019). "Again, the implication is that the Weaver syndrome Ezh2(p.V262M) mutant manifests a milder phenotype than complete Ezh2 loss of function." (PMID 31575610, 2019). "EZH2 missense mutations in humans cause the rare congenital disorder Weaver Syndrome, leading to neurological abnormalities such as macrocephaly, speech delay, intellectual disability, and poor coordination and balance." (PMID 31891591, 2019). "A Weaver syndrome-associated mutation affecting the H3K36-sensing pocket in EZH2 is also reported to disrupt the crosstalk between PRC2 and NSD1 on chromatin." (PMID 31575610, 2019). "Taken together, these data support a partial loss-of-function phenotype for the Weaver syndrome mutant EZH2." (PMID 31575610, 2019). "To date, three studies have attempted to address this by examining the enzymatic activities of Weaver syndrome-associated EZH2 mutant proteins." (PMID 31575610, 2019). "In this study, CRISPR-mediated genome editing was used to generate mice harbouring a Weaver syndrome patient-specific missense mutation targeting the SET domain of EZH2 (p.Val262Met)." (PMID 31575610, 2019). "Consistent with a role for EZH2 in human oocytes, we demonstrate that de novo germline mutations in EZH2 occurred in the maternal germline in some cases of Weaver syndrome." (PMID 30005706, 2018). "Significantly, de novo germline mutations in EED or EZH2 in humans lead to Cohen-Gibson and Weaver syndromes, characterised by overgrowth, skeletal defects and learning/cognitive disabilities." (PMID 30005706, 2018). "In humans, de novo germline mutations in EZH2 lead to Weaver Syndrome (OMIM 28229590) and de novo germline mutations in EED lead to Cohen-Gibson syndrome, both of which are characterised by overgrowth." (PMID 30005706, 2018). "Heterozygous missense mutations in Ezh2 cause Weaver syndrome, a rare condition characterized by tall stature, macrocephaly, accelerated osseous maturation." (PMID 29101351, 2017). "In 2011, mutational analysis of EZH2 in 48 Weaver syndrome patients revealed 44 missense and four truncated mutations." (PMID 27239242, 2016). "Genome-wide associated studies have implicated EZH2 in the control of height and mutations in EZH2 cause Weaver syndrome, which includes skeletal overgrowth." (PMID 27897169, 2016). "This approach showed that there is an urgent need for the uniformed positioning of currently known EZH2 mutations (somatic—in tumors, as well as germline mutations in the Weaver’s syndrome)." (PMID 27239242, 2016). "Our observations also provide interesting insights into the pathophysiology of Weaver syndrome, which can be caused by heterozygous missense mutation in EZH2 (refs 6, 7)." (PMID 27897169, 2016). "This included one case with an initial diagnosis of Sotos syndrome (R121), but on finding a mutation in the EZH2 gene the case was re-evaluated and determined to be Weaver syndrome." (PMID 26380986, 2015). "There are some reports of NSD-1 mutations in individuals with Sotos and Weaver syndromes and more recently mutations in the EZH2 gene in three families with Weaver syndrome have been identified." (PMID 25009745, 2014). "Overgrowth disorders, Sotos syndrome and Weaver syndrome, are caused by heterozygous mutations in the HMT NSD1 (Sotos and Weaver syndromes) and EZH2 (Weaver syndrome)." (PMID 25750614, 2014). "Our data establish EZH2 mutations as the cause of Weaver syndrome and provide further links between histone modifications and regulation of human growth." (PMID 22190405, 2011).
Weaver syndrome (continued). "We performed exome sequencing in four individuals with Weaver syndrome, identifying a mutation in the histone methyltransferase, EZH2, in each case." (PMID 22190405, 2011). "The EZH2 mutation spectrum in Weaver syndrome shows considerable overlap with the inactivating somatic EZH2 mutations recently reported in myeloid malignancies." (PMID 22190405, 2011). "Given that the myeloid malignancies associated with somatic EZH2 mutations usually occur in later life it is possible that individuals with Weaver syndrome are at increased risk of myeloid and/or other malignancies." (PMID 22190405, 2011). "Weaver syndrome is a rare congenital overgrowth disorder caused by pathogenic EZH2 variants." (PMID 41300605, 2025). "This inheritance pattern strongly supports the pathogenic role of the de novo EZH2 variant as the primary cause of the patient’s Weaver syndrome, whereas the maternally inherited ALDH18A1 variant represents an incidental finding of uncertain clinical significance in this case." (PMID 41300605, 2025). "Consequently, this EZH2-associated DNAm signature represents a powerful first-tier diagnostic tool, capable of improving diagnostic yield and efficiency for Weaver syndrome and other PRC2-related disorders." (PMID 40922349, 2025). "The neurodevelopmental abnormalities observed in Weaver syndrome are hypothesized to stem from the dysregulation of PRC2 function caused by EZH2 variants." (PMID 40922349, 2025). "Pathogenic variants in the EZH2 gene are the principal cause of Weaver syndrome." (PMID 40922349, 2025). "We hypothesized the VUS had a gain-of-function effect on EZH2, opposite to the loss-of function effect of variants causing Weaver syndrome." (PMID 37022461, 2024). "Heterozygous EZH2 loss of function variants cause Weaver syndrome (WVS), according to current data, most likely due to PRC2 defects with consequently altered WNT/beta-catenin signaling in stem cells that result in overgrowth of the skeleton, visceral organs and/or the brain." (PMID 38894719, 2024). "The mechanism by which EZH2 variants cause Weaver syndrome has been a matter of discussion." (PMID 38015625, 2024). "We generated a mouse model for the most common Weaver syndrome missense variant, EZH2 p.R684C." (PMID 38015625, 2024). "Previous studies have identified EZH2 as one of the causative genes of Weaver syndrome, a developmental disorder characterized by macrocephaly, dysmorphic facial features, accelerated skeletal maturation, limb anomalies, developmental delay, and intellectual disability." (PMID 37326884, 2023). "Furthermore, we identified, in a patient with clinical suspicion of Weaver syndrome, a heterozygous de novo mutation in the enhancer of zeste homolog 2 (EZH2) gene, a histone methyltransferase responsible for histone H3 at lysine 27 (H3K27) trimethylation." (PMID 36833222, 2023). "EZH2 mutations are known to be able to cause a syndrome called Weaver’s syndrome." (PMID 36242045, 2022). "Taken together, our findings point at precise dysregulations in neuronal homeostasis upon EZH2 loss that may represent an entry point for the study of the intellectual disability characterizing Weaver Syndrome." (PMID 35645710, 2022). "EZH2 mutations in Weaver’s syndrome cause characteristic DNA methylation changes." (PMID 36242045, 2022). "Indeed, a possible manifestation of neuronal overmigration, cortical polymicrogyria, is found in Weaver syndrome, which is caused by mutations in the EZH2 gene, and in a neuroactive drug embryopathy, fetal hydantoin syndrome." (PMID 33658318, 2021). "Accordingly, mutations of EZH2 in Weaver syndrome are associated with overgrowth and macrocephaly." (PMID 32766754, 2020). "Similarly, an individual with a maternally inherited duplication encompassing DNMT3A exhibits a growth failure phenotype marked by developmental delay, despite also possessing a paternally inherited Weaver syndrome-related point mutation in EZH2." (PMID 31575610, 2019).
Weaver syndrome (continued). "Moreover, de novo germline mutations in human EZH2 result in Weaver syndrome, characterised by growth and skeletal defects and intellectual disability." (PMID 29515677, 2018). "Interestingly, germline de novo mutations in either EED or EZH2 result in Weaver syndrome, characterised by growth and congenital defects and cognitive deficit in affected humans." (PMID 30236109, 2018). "In humans, the EZH2 mutation may occur in a germline, resulting in clinical features known as the Weaver syndrome, originally described in 1974." (PMID 27239242, 2016). "Thus, the molecular pathophysiology of EZH2 mutations in Weaver syndrome requires further investigation." (PMID 27897169, 2016). "Similarly, in humans, heterozygous partial loss-of-function variants in EZH2 increase skeletal growth in Weaver syndrome, whereas, in mice, homozygous loss of Ezh1 and Ezh2 impairs growth plate function by inhibiting proliferation and hypertrophy of growth plate chondrocytes." (PMID 36927955, 2023). "In addition to the molecular evidence that EZH2 is pivotal for regulating corticogenesis in mice, haploinsufficiency of EZH2 in humans causes intellectual disability in the context of Weaver Syndrome (WS), a rare disease characterized by overgrowth, facial dysmorphism, and intellectual disability." (PMID 35645710, 2022). "Finally, it was shown that a histone methyltransferase encoded by the causal gene for Weaver syndrome EZH2 interacts the polycomb repressive complex 2 (PRC2) and directly controls DNA methylation, implicating epigenetic regulation of gene expression in baseline refractive eye development." (PMID 34107987, 2021). "This case broadens the clinical spectrum of Weaver syndrome by highlighting severe camptodactyly and complex brain malformations as possible EZH2-related manifestations." (PMID 41300605, 2025). "Caused by mutations in EZH2 (WVS; OMIM 277590), Weaver’s syndrome is an autosomal dominant disease characterized by learning disabilities, dysmorphic facial features and general overgrowth, which can include tall stature, obesity and macrocephaly." (PMID 40469903, 2025). "Mouse models encoding pathogenic EZH2 missense variants, which are predicted to result in loss of function of the PRC2 complex, phenocopy Weaver syndrome and cause excess osteogenesis and skeletal overgrowth." (PMID 41329158, 2025). "An EZH2 missense mouse model of Weaver syndrome exhibits skeletal overgrowth, excess osteogenesis, and a characteristic transcriptomic profile that is reversed with a KDM6A/6B inhibitor." (PMID 38015625, 2024). "EZH2, EED2, and SUZ12 mutations cause the neurodevelopmental disorders Weaver syndrome (OMIM #277590), Cohen-Gibson syndrome (OMIM #617561), and Imagawa-Matsumoto syndrome (OMIM #618786)." (PMID 38690732, 2024). "To identify gene expression changes responsible for enhanced osteogenesis in Weaver syndrome, we differentiated Ezh2R684C/+ and Ezh2+/+ BM-MSCs toward osteoblasts for 14 days and then performed transcriptome profiling with RNA-Seq." (PMID 38015625, 2024). "In the first study, we identified an individual with an undergrowth phenotype and a VUS [p.Ala738Thr] in EZH2 [MIM: 601573], a gene in which pathogenic variants are associated with Weaver syndrome [MIM: 277590], characterized by an overgrowth phenotype." (PMID 37022461, 2024). "In some overgrowth syndromes, variants in epigenetic regulators are associated with disease occurrence, such as variants of histone methyltransferases NSD1 in Sotos syndrome and EZH2 in Weaver syndrome." (PMID 38791606, 2024). "The PCR2 complex episignature, which includes Cohen–Gibson syndrome (EED) and Weaver syndrome (EZH2), presented with a ~4% overlap in DMPs." (PMID 37762546, 2023).
Weaver syndrome (continued). "However, it is likely that changes in neuronal morphogenetic processes, especially the dendritic development induced by neuronal Ezh2 deletion, might underlie some of the cognitive behavior phenotypes in adult Ezh2Δ/Δ mice or potentially in patients with Weaver Syndrome or ASD." (PMID 37326884, 2023). "Weaver syndrome (MIM# 277590), is a rare overgrowth disorder that is caused by de novo mutations in EZH2, a histone methyltransferase." (PMID 36064314, 2022). "As previously reported, EZH2 is overexpressed in Weaver syndrome and primary cutaneous follicle center lymphoma." (PMID 33849532, 2021). "In accordance with the overgrowth phenotype in Weaver syndrome, conditional KO of Ezh2 in mice accelerated proliferation of neuronal precursors in the cerebral cortex at the expense of self-renewal of progenitors." (PMID 33263776, 2021). "Pathogenic mutations in EZH2, SUZ12 and EED are seen in overgrowth syndromes with variable ID, such as Weaver syndrome and Cohen–Gibson syndrome." (PMID 32766754, 2020). "In humans, heterozygous mutations in the EZH2, EED and SUZ12 genes cause congenital overgrowth, often marked by features that are typical of those observed in Weaver syndrome." (PMID 31575610, 2019). "Weaver syndrome (MIM #277590) is an autosomal dominant condition caused by germline monoallelic mutations affecting the genes encoding the core PRC2 subunits, EZH2, EED and SUZ12." (PMID 31575610, 2019). "Collectively, they determined that Weaver syndrome mutant EZH2 exhibits impaired global histone methyltransferase activity both in vitro and in vivo." (PMID 31575610, 2019). "Because EZH2 is the primary methyltransferase (writer) of H3K27me3, we reasoned that the characteristic features of Weaver syndrome might be attributed to decreased or displaced H3K27me3 at key genomic loci." (PMID 38015625, 2024). "The Sotos and Weaver syndromes, overgrowth syndromes produced by germline mutations in the NSD1 and EZH2 genes, respectively, encode histone methyltransferases and have considerable clinical overlap with MC, giving rise to a high, broad forehead, and prominent chin." (PMID 38791606, 2024). "Similar to EZH2, several mutations in EED have also been identified in patients with Weaver syndrome, while mutations in SUZ12 have been associated with a Weaver-like syndrome presenting with macrocephaly, postnatal overgrowth, and skeletal abnormalities." (PMID 36845425, 2023). "Moreover, this site is in a genomic region containing the binding domain of EZH2, a gene that is involved in the etiology of memory impairments, autism and Weaver syndrome, an overgrowth/intellectual disability syndrome." (PMID 35757177, 2022). "The fact that we see a negative correlation between Cri du chat patient’s methylation and Weaver’s syndrome methylation suggests that EZH2 activity may somehow be changed in the Cri du chat patients." (PMID 36242045, 2022). "Likewise, two of three reported Weaver syndrome-associated mutations in SUZ12 are nonsynonymous substitutions within its VEFS domain, a key functional domain for its association with EZH2 and EED, which, when deleted, abolishes the enzymatic activity of PRC2." (PMID 31575610, 2019). "Indeed, such a case was recently reported and it was shown that global EZH2 protein levels in the respective Weaver syndrome patient sample were comparable to those in control samples." (PMID 31575610, 2019). "Importantly, heterozygous Ezh2(p.V262M) mice also exhibit postnatal overgrowth, a key feature of Weaver syndrome." (PMID 31575610, 2019). "Germline heterozygous mutations in the genes encoding core PRC2 members (EZH2, EED and SUZ12), NSD1 and DNMT3A have been implicated in a triad of highly phenotypically related human developmental disorders: Weaver syndrome, Sotos syndrome and Tatton-Brown–Rahman syndrome, respectively." (PMID 31575610, 2019).
Weaver syndrome (continued). "Our data suggest that the mutations causing Weaver syndrome are not simple loss-of-function mutations because, in mice, heterozygous—or even homozygous—loss-of-function mutations in Ezh2 do not have a skeletal phenotype unless Ezh1 is also ablated." (PMID 27897169, 2016). "Moreover, muted EZH2 led to Weaver Syndrome that had intellectual disability as one of its common features." (PMID 27266699, 2016). "The likely causal variant may even be fixed in other organisms e.g. EZH2:NM_004456.4:c.2233 G > A;p.(Glu745Lys) variant in family F1294 with Weaver syndrome was difficult to interpret because it corresponds to the normal allele in marmosets." (PMID 37644014, 2023). "Both EZH2 and NSD1 catalyze methylations of H3K36 and H3K27, suggesting that mutations in writers of these two chromatin marks might cause overgrowth conditions, resembling Sotos or Weaver syndromes." (PMID 33937229, 2021). "Interestingly, pathogenic variants in EZH2 have been found in individuals with overgrowth without other clinical features of Weaver syndrome, indicating a wide spectrum of the disorder." (PMID 33194904, 2020). "Interestingly, EZH2 mutations (which cause Weaver syndrome) do not seem to affect the epigenetic clock in our screen." (PMID 31409373, 2019). "Although simple haploinsufficiency is not thought to be the mutational mechanism underlying Weaver syndrome, there is a report of an individual who is haploinsufficient for EZH2 and exhibits some of the features of Weaver syndrome, including overgrowth and intellectual disability." (PMID 31575610, 2019). "However, loss of EZH2 function in oocytes led to decreased birth weight in mice, rather than increased birth weight typically observed in Weaver syndrome." (PMID 30236109, 2018). "Inhibition of EZH2 by GSK-126, a pharmacological analogy to Weaver syndrome, stimulates osteoblast differentiation in mice, while GSK-J4 reduced osteogenesis in a mouse model of Saethre-Chotzen craniosynostosis (MIM 101400)." (PMID 38015625, 2024). "Although a large degree of phenotypic overlap exists between Sotos syndrome and Weaver syndrome, NSD1 and EZH2 regulate different methylation sites." (PMID 25750614, 2014). "Such alternative catalytic activity need not be mutually exclusive with the role of EZH2 in histone methylation, and it is conceivable that both contribute toward the phenotype of Weaver syndrome." (PMID 38015625, 2024). "Neonatal hypoglycemia has anecdotally been reported in Weaver syndrome (OMIM #277590), an overgrowth syndrome with variable intellectual disability and characteristic facial features, caused by heterozygous EZH2 pathogenic variants, but CHI has not been documented in the literature, so far." (PMID 37065762, 2023). "Notably, JARID2 exhibited the highest overlap with CHARGE (~7%, CHD7), BAFopathy (~4%, including ARID1A, ARID1B, SMARCB1, SMARCA2, SMARCA4), and the PCR2 complex, which houses Cohen–Gibson syndrome (COGIS) and Weaver syndrome (WVS) (~4%, EED, EZH2)." (PMID 37762546, 2023).